EWSR1 (EWS RNA binding protein 1)
Diseases named in the same sentence as EWSR1 in open-access papers (continued):
Sharing a sentence is not in itself a finding about the gene and the disease.
tumor (continued). "Taken together, these results suggest that EWSR1 expression influences tumor progression in NB and is partially regulated by MYCN oncoprotein." (PMID 29212266, 2017). "In 85–90% of EFTs cases, the tumor is characterized by a translocation involving the EWSR1 (EWS RNA-Binding Protein 1) gene on chromosome 22, and an ETS (E26 transformation-specific)-family gene such as FLI-1 or ERG1." (PMID 29263409, 2017). "Reverse transcriptase polymerase chain reaction (RT-PCR) was performed at an outside reference laboratory using primers specific for the EWSR1-WT1, EWSR1-FLI1, and EWSR1-ERG fusion transcripts after the slide was macrodissected for tumor enrichment." (PMID 27403364, 2016). "Fluorescence in situ hybridization (FISH) testing was performed on 100 interphase cells from the pleura-based tumor using dual color break-apart probes for 5′EWSR1 and 3′EWSR1 gene regions at 22q12." (PMID 27403364, 2016). "De Vito demonstrated direct binding of the EWSR1-Fli1 fusion protein to the promoter region of Let-7a, a known growth/tumor suppressor with important roles in differentiation, and this resulted in repression of pri-let-7a-a and mature let-7a." (PMID 26204834, 2015). "Candidate tumour suppressor miRNAs normally repressed by EWSR1-Fli1, included miR-22, shown to have tumour suppressor properties in other cancers." (PMID 26204834, 2015). "The only EWSR1 rearranged tumor that is likely to show overlapping clinical presentation and immunohistochemical features with DSRCT is EW/PNET." (PMID 26413364, 2015). "In contrast, both tumour types harbour EWSR1 (Ewing sarcoma breakpoint region 1; 22q12.2) rearrangement." (PMID 22569967, 2012). "Some oncogenes and tumor suppressors with cancer-specific alternative splicing, such as EWSR1, CDKN1A, and GLTSCR2, are present in more types of cancer." (PMID 19266097, 2009). "Known to be translocation-associated neoplasms, they share a common non-random translocation leading to the fusion of the EWSR1 gene on the 22q12 region, with one of the many members of the ETS family of transcription factors." (PMID 40950824, 2025). "One tumor each had an EWSR1::ATF1 (8%) and EWSR1::PBX3 (8%) fusion." (PMID 40748380, 2025). "Notably, molecular analysis of the tumor identified an atypical EWSR1::FLI1 rearrangement, a finding previously unreported in this malignancy, along with several pathogenic variants associated with hematologic malignancies." (PMID 40630716, 2025). "Later, the EWSR1 translocation was identified in the tumor cells with unknown partners and the patient received chemotherapy according to the Ewing 2008 protocol in combination with surgery and proton beam radiotherapy." (PMID 40134582, 2025). "Furthermore, the fusion of the CREB gene family with EWSR1 or FUS gene partners leads to a wide variety of tumor pathogenesis." (PMID 41341384, 2025). "Consistent with the results in cultured cells, the ability of ITZ to suppress TC-71 xenograft growth was counteracted by ectopic expression of EWSR1::FLI1, indicating that the reduced levels of EWSR1::FLI1 following ITZ treatment were responsible for the reduction in tumor growth." (PMID 39894896, 2025). "Seven neoplasms showed EWSR1::CREM fusion by RNA-seq, and four tumors were confirmed by FISH." (PMID 41341384, 2025). "Fluorescence in-situ hybridization using the EWSR1 breakage probe showed a separation of the red and green signals (arrows), suggestive of EWSR1 translocation, with EWSR1 gene split signal-positive cells accounting for about 20% of the total number of tumor cells." (PMID 41426591, 2025). "We experienced a case of gastric epithelioid mesenchymal tumor with EWSR1::CREM fusion genes that did not fit the diagnostic criteria of established tumor entities." (PMID 40242428, 2025).
tumor (continued). "Neoplasms with fusions between Ewing sarcoma breakpoint region 1 (EWSR1) or fused in sarcoma (FUS) genes and genes encoding the CREB family of transcription factors (ATF1, CREB1, and cAMP-responsive element modulator [CREM]) are one such tumor type." (PMID 40242428, 2025). "Isolated tumor cells with lower Pax3::Foxo1 expression had a higher oncogenic capability in allograft models and more migratory potential in vitro, a phenomenon that is also seen for the EWSR1::FLI1 fusion in Ewing sarcoma." (PMID 38916046, 2024). "This includes exact tumor location, lack of EWSR1 status for diagnostic confirmation, histologic response to chemotherapy, radiation dosing, type of chemotherapy received, or patients' involvement in clinical trials." (PMID 39436736, 2024). "Whether these gonadal neoplasms are part of the EWSR1/FUS::ATF1/CREM fusion-driven tumor spectrum with subtle organ-specific phenotypic differences remains controversial." (PMID 39031200, 2024). "This tumor exhibits indolent growth and a slow clinical course, with characteristic infiltration by clear or eosinophilic tumor cells within a markedly hyalinized stroma and an EWSR1 gene rearrangement." (PMID 39723381, 2024). "If an EWSR1::ATF1 fusion is detected in pulmonary myxoid sarcoma with EWSR1::CREB1 translocation, the tumor may be classified as “pulmonary myxoid sarcoma with EWSR1::CREB translocation”." (PMID 38421462, 2024). "FISH analysis of tumor tissue from the second SMN revealed the EWSR1/ERG fusion gene." (PMID 39596402, 2024). "However, the intensity of ERG expression is typically weaker than that observed in the endothelium of surrounding vessels (or that observed in EWSR1::SMAD3-rearranged tumor) and comparison with these structures is diagnostically useful." (PMID 39264472, 2024). "Additionally, EWSR1::FLI1 recruits the BAF complex to tumor-specific enhancers to promote activation of target genes." (PMID 36672331, 2023). "BARD1 as a putative tumor suppressor, interacts with the N-terminus of EWSR1::FLI1." (PMID 36672331, 2023). "The interaction between the permissive cellular environment and the EWSR1-ETS tumour-specific chimeric transcription factors leading to cellular transformation and ES is poorly understood, although is no doubt important illustrated by the high incidence of ES in Europeans compared to Africans." (PMID 36765727, 2023). "Future studies will also need to investigate if the expression of ETS1 and the other transcription factor genes data suggests some EWS tumor cells express at higher levels than EWS cell lines is a result of heterogenous EWSR1:FLI1/ERG expression and/or due to the transduction of external stimuli." (PMID 38187702, 2023). "Notably, the presence of a CREB-binding site in the IL-6 promotor region together with the high expression of CREB triggered by the EWSR1::CREB1 fusion has been proposed to explain the IL-6 overexpression observed in this rare tumor type." (PMID 36690805, 2023). "EWSR1::FLI1 expression can vary between cells within a tumor." (PMID 36483025, 2022). "It is conceivable that the EWSR1/FUS::NFATC2 fusion might be a very early event in tumor initiation, and additional events are required for progression." (PMID 36555836, 2022). "A few pioneer studies have exemplified fusion-circRNAs (f-circRNAs) derived from tumor-associated chromosomal translocations, such as PML-RARα, MLL-AF9, EWSR1/F LI1, and EML4/ALK1, and these f-circRNAs were circularized by transcribed exons of distinct genes affected by the translocations." (PMID 36613512, 2022). "However, the role of EWSR1 protein expression in tumor, especially in epithelial cancers is rarely reported." (PMID 34612781, 2021). "On the contrary, the more poorly differentiated EWSR1-FLI1high cells, which by far exceed the EWSR1-FLI1low cells in a tumor, are clearly in a proliferative state, showing robust cell-to-cell adhesion, and lack the migration properties of the EWSR1-FLI1low cells." (PMID 33801953, 2021).
tumor (continued). "MN1 and EWSR1 are both involved in fusions in other tumor entities." (PMID 34417833, 2021). "Second, we wanted to examine whether a tumor with an EWSR1-CREM fusion gene might overexpress the fusion protein, resulting in stronger immunohistochemical CREM staining intensity than seen in the corresponding normal tissues." (PMID 34261344, 2021). "It is an aggressive tumor typically characterized by a fusion of the Ewing sarcoma breakpoint region 1 (EWSR1) with an erythroblast transformation specific (ETS) transcription factor gene, most frequently (>95%) the friend leukemia virus integration 1 (FLI1) gene." (PMID 34359637, 2021). "In addition, univariate Cox regression analysis showed that tumor size, differentiation degree, T stage, N stage, TNM stage, AFP overexpression, Ki67 expression, and EWSR1 overexpression were each significantly associated with OS (P < 0.05)." (PMID 34612781, 2021). "The tumor was found to be positive for the EWSR1/ATF1 fusion gene." (PMID 33478436, 2021). "Knockdown or ectopic expression of EWSR1 or MAZ rescued tumor cells from these changes." (PMID 31709724, 2019). "Mechanistically, transcription factor p110 CUX1, a proteolytic product of p200 CUX1, promotes expression of glycolytic genes, while circ‐CUX1 facilitates EWSR1‐mediated MAZ transactivation to alter expression of p200 CUX1 and other genes associated with tumor progression." (PMID 31709724, 2019). "As alluded to above, fusion of EWSR1 to WT1 in this pediatric malignancy abrogates the tumor suppressor role of WT1 as well as the RNA-binding capacity of EWSR1, and generates an oncogenic molecule capable of binding and transactivating WT1 target genes, including the IGF1R promoter." (PMID 29455671, 2018). "However, there can be significant morphologic and immunohistochemical overlap between groups of EWSR1-rearranged neoplasms, with important prognostic and therapeutic implications." (PMID 28141799, 2017). "Care should therefore be taken in the interpretation of FISH for EWSR1 rearrangement with INI1-deficient neoplasms, and in general the FISH patterns for these tumours have been complex, differing from the more uniform and simple split signals of typical EWSR1-rearranged neoplasms." (PMID 28141799, 2017). "Interestingly, a group of authors (as yet unpublished) have recently demonstrated EWSR1 rearrangement in a subset of 2 of 9 tumours." (PMID 27239359, 2016). "Furthermore, the ectopic expression of the EWSR1 fusion in mouse MSC led to tumor development with overlapping features with EWS, namely CD99 overexpression." (PMID 24498265, 2014). "It remains to be determined whether these S-100 protein positive tumors harboring EWSR1 translocations represent a clinical, morphologic, immunophenotype, and genetic spectrum of one tumor or are two distinct tumors." (PMID 21403834, 2011). "Beyond its diagnostic utility, EWSR1::FLI1 may also establish targetable molecular dependencies, offering promising avenues for therapeutic innovation in this otherwise genomically sparse tumor." (PMID 41514642, 2025). "Fusions between members of the FET gene family (EWSR1 and FUS) and genes encoding for the CREB-transcription factor family (ATF, CREB1, and CREM) have been reported in a variety of clinically and pathologically distinct neoplasms of mesenchymal, epithelial and mesothelial origin." (PMID 39031200, 2024). "It was commented that the significance of this rearrangement, as well as that of the focal loss of INI-1 nuclear expression, was not clear, and that the findings are not diagnostic of ATRT or Ewing Sarcoma, or other defined neoplasms characterized by EWSR1 rearrangements." (PMID 38639853, 2024). "CircCUX1 interacts with EWS RNA-binding protein 1 (EWSR1) to enhance its binding with MYC-associated zinc finger protein (MAZ), leading to the increased transactivation of MAZ and the subsequent transcriptional changes in genes linked to tumor progression, including CUX1." (PMID 39452835, 2024).
tumor (continued). "The fluorescence in-situ-hybridization with a EWSR1 dual color break-apart probe (ZytoVision®, Bremerhaven, Germany) was performed whereby no EWSR1 gene re-arrangement could be detected in the analyzed tumor specimen." (PMID 34780010, 2022). "However, neoplasms harboring EWSR1-CREM/FUS-CREM fusions are rare and poorly characterized." (PMID 34228212, 2022). "Moreover, EwS tumors have well-established genetic aberrations that can be used for comparison, most notably the tumor-defining chromosomal translocation between EWSR1 and an Ets family member gene (most commonly FLI1), and a small number of recurrent CNAs46–48." (PMID 34050156, 2021). "Our results are applicable to other oncogenic ES fusion-proteins driven by EWSR1, as genetic or pharmacological inhibition of C1GALT1 also decreases cell viability and tumor growth of ES cells that harbor an EWSR1::ERG fusion." (PMID 39894896, 2025). "NR4A3 functions as a tumor suppressor in BLCA by enhancing endoplasmic reticulum stress and inhibiting anoikis resistance through the EWSR1/Ezrin pathway." (PMID 40762284, 2025). "In MLS, SWI/SNF complexes can be redistributed by FUS::DDIT3 from adipogenic promotor regions, while in EWS, they can be aberrantly recruited by EWSR1::FLI1 to tumor-specific enhancers." (PMID 40988026, 2025). "Central to its development are genetic fusions, particularly involving EWSR1::CREB1, which drive tumor proliferation." (PMID 40429661, 2025). "Our study reveals a therapeutically targetable mechanism that promotes EWSR1::FLI1 expression and ES tumor growth." (PMID 39894896, 2025). "Inhibition of C1GALT1 using a genetic or pharmacological inhibitor, such as ITZ, reduces SMO O-glycosylation, Hh signaling, and EWSR1::FLI1 expression, resulting in decreased ES cell viability and tumor growth in mice." (PMID 39894896, 2025). "For example, the EWSR1::KLF15-fused tumors involved pediatric patients, showed characteristic morphology of corded aggregates of tumor cells within a myxohyaline background and had undifferentiated round cells in a subset." (PMID 39636306, 2025). "By contrast, HCCC tumor cells express P63, P40, and CK5/6, and are characterized by EWSR1 rearrangement." (PMID 40738062, 2025). "Herein, we present two rare cases of primary CNS NEpTs harboring EWSR1::PATZ1 fusions, a unique clinical course, and co-existing previously undescribed genetic and methylation alterations in this tumor type." (PMID 40575153, 2025). "Pharmacological inhibition of C1GALT1 using the FDA-approved anti-fungal drug itraconazole decreases EWSR1::FLI1 expression in human ES cell lines resulting in cell death, and suppresses ES tumor growth in xenograft mouse models." (PMID 39894896, 2025). "In a related study of 39 cases, sub-classification based on DNA methylation status was highly accurate in terms of predictive clustering of EWSR1-CREB, and related fusions as CSS versus other tumor types." (PMID 38946804, 2024). "This tumor is characterized in most cases by a RREB1::MRTFB fusion, while there is EWSR1 gene rearrangement in a smaller subset of cases." (PMID 38491228, 2024). "Regarding gene amplification, EWSR1, FLT3, GPC3, HIF1A, HLF, and MEN1 have been reported in CaPa and other neoplasias as well." (PMID 38397997, 2024). "A distinct feature of our series is the examination of the tumor samples, not only for histological diagnosis but also for the presence of the pathognomonic gene translocation FUS::DDIT3 or EWSR1::DDIT3." (PMID 36907960, 2023). "In summary, evidence exists that HIF-1-a, like EWSR1::FLI1, contributes to tumor heterogeneity in EwS." (PMID 36915100, 2023). "MS0621 reprograms the EWSR1::FLI1-regulated alternative splicing pattern, decreasing tumor-characteristic intron retention and altering the inclusion of exons harboring highly conserved sequences." (PMID 36793594, 2023).
tumor (continued). "CircCUX1 interacted with EWS RNA binding protein 1 (EWSR1) to stimulate MYC-related zinc finger protein (MAZ) trans-activation, resulting in CUX1 transcription modification and other tumor progression-related genes being transcribed." (PMID 37091173, 2023). "One of the recurring fusion genes in cancer is EWSR1::CREM, which has been detected in a wide variety of tumor types ranging from low-grade indolent to aggressive." (PMID 36966162, 2023). "The critical dependence on EWSR1::FLI1 and its exclusive expression in tumor cells makes it an attractive candidate for drug development." (PMID 36793594, 2023). "Intriguingly, low expression of this EWSR1::FLI1 target gene impaired EwS vessel morphology and increased tumor hypoxia." (PMID 36915100, 2023). "eGFP staining was used to label all tumor cells within the tumor, while FLI1 staining was implemented to detect the EWSR1-FLI oncofusion in tumor cells." (PMID 35285802, 2022). "The EWSR1::ETS oncogenic fusion is so far the only recurrent and tumor specific genetic alteration in ES." (PMID 35455947, 2022). "The Ewing Sarcoma family of tumors (ESFT) encompasses tumors with common small-cell phenotype and molecular features that include balanced reciprocal translocations between EWSR1 and genes of the ETS family of transcription factors." (PMID 34374640, 2022). "The most common tumor-specific chimeric transcription factor, EWSR1-FLI1, consists of the Ewing sarcoma breakpoint region 1 protein (EWSR1) and an ETS family gene such as the Friend leukemia integration 1 transcription factor (FLI1)." (PMID 36497417, 2022). "Supervised analysis on MN tumor samples identified 2,249 differentially expressed genes (p-value < 0.05) in SRF-fused positive tumors with respect to EWSR1-fused positive tumors." (PMID 36421692, 2022). "To detect the presence of EWSR1, ATF1 and CREB1, we counted 100 nuclei in tumor cells and that showed a pair of fused and split signals, and calculated the percentage of split signals." (PMID 32803839, 2020). "Subsequently, split signals of EWSR1, ATF1 and CREB1 in tumor cells of the large lesion were 5%, 2% and 0%, respectively." (PMID 32803839, 2020). "Using formalin-fixed, paraffin-embedded 4-mm-thick tumor samples, dual-color break-apart fluorescence in situ hybridization (FISH) was used to investigate EWSR1 and FUS1 gene rearrangements." (PMID 31915021, 2020). "Circ‐CUX1 enhanced the expression of CUX1 at transcriptional level, and tumor‐promoting functions of circ‐CUX1 were mediated, at least in part, through interacting with EWSR1 protein in NB cells." (PMID 31709724, 2019). "In the current study, we report three patients with tumors carrying the EWSR1-NFATC2 gene translocation, including one rare primary tumor of soft tissues." (PMID 31049020, 2019). "Among the 8 tumors, 3 had EWSR1-CREM fusion, 4 had EWSR1-CREB1 fusion, and one tumor showed EWSR1-ATF1 fusion." (PMID 30219084, 2018). "EWSR1 rearrangement testing (FISH and/or RT–PCR) was performed in 125 undifferentiated neoplasms, of which 62 were composed of spindle cells, 26 of round cells, 7 of pleomorphic cells, with the remainder having mixed morphology." (PMID 28141799, 2017). "Using the R2 platform, we analyzed the expression level of EWSR1 and FLI1 in published NB tumor and cell line gene expression datasets." (PMID 29212266, 2017). "A well-known EWSR1-ETS targeted pathway is the IGF pathway, which is involved in tumor growth, metastasis and angiogenesis." (PMID 26193259, 2015). "Diagnosis was confirmed upon fluorescent in situ hybridisation (FISH) testing which revealed a rearrangement of the EWS gene, most commonly occurring due to translocation of EWSR1, a fusion transcription factor found in 85% of Ewing's family tumours." (PMID 26236533, 2015). "At the transcriptome level, EWSR1-ETS influences various pathways involved in intracellular processes and tumor microenvironmental processes that are needed for EWS development and maintenance." (PMID 26193259, 2015).